CCND1 (cyclin D1)
Diseases named in the same sentence as CCND1 in open-access papers (continued):
Sharing a sentence is not in itself a finding about the gene and the disease.
non-small cell lung carcinoma (continued). "FAM129B has been identified as a key factor that promotes cancer cell invasion in non-small-cell lung cancer (NSCLC) by facilitating the phosphorylation of focal adhesion kinase (FAK), which upregulates Matrix metalloproteinase-2 (MMP-2) and Cyclin D1." (PMID 39941813, 2025). "CCND1 and CDK2 were both expressed in non-small cell lung cancer, and CCND1 was highly expressed in non-small cell lung cancer tissues (42%)." (PMID 38245694, 2024). "In non-small cell lung cancer, cytoplasmic WNT1 is also significantly activated and correlates with overexpression of β-catenin, c-myc and cyclin D1, and lowers 5-year survival." (PMID 37345102, 2023). "The combination of metformin and pemetrexed exhibited an antiproliferative effect by affecting the cell cycle in non-small-cell lung cancer via downregulation of CCNA2 and CCND1, and the upregulation of CDKN1B." (PMID 35480884, 2022). "In BC and non-small cell lung cancer (NSCLC), knockdown of HOXB5 significantly suppressed the β-catenin protein and its downstream targets c-Myc and CCND1, thereby inhibiting cell proliferation, migration, invasion, and EMT of the cancer cells." (PMID 34617205, 2022). "Curcumin also enhances the effects of cisplatin by targeting the CSCs CD166+/EpCAM+ subpopulation in non-small cell lung cancer cell lines (NSCLC) by p21- and cyclin D1-mediated tumor cell inhibition." (PMID 32127962, 2020). "These aptamers significantly suppress the growth of human non-small cell lung cancer (NSCLC) tumors in vivo by selectively inhibiting the activation of Stat3 and its downstream proteins such as Bcl-2, Bcl-xL, Mcl-1, survivin, VEGF, Cyclin D1, and c-myc." (PMID 31640176, 2019). "In non-small cell lung cancer (NSCLC), GCN5 enhances cell proliferation and G1/S transition by regulating the expression of cell cycle proteins like cyclin D1, E1 and E2F1." (PMID 27322556, 2016). "miR-138 inhibited cancer cell growth and tumorigenesis in non-small cell lung cancer and nasopharyngeal cancer by targeting 3-phosphoinositide-dependent protein kinase-1 (PDK1) and CCND1." (PMID 24941171, 2014). "The present study confirmed that the protein expression of Cyclin D1, CDK6 and Bcl-2 were reduced by overexpression of miR-34a, which is consistent with previous studies in non-small cell lung cancer A549 cells and neuroblastoma NLF cells." (PMID 25268950, 2014). "This in turn leads to reduction in the protein levels of cyclin D1 (CCND1) and cyclin-dependent kinase 6 (CDK6), which regulates the phosphorylation of retinoblastoma protein (pRb), as seen in non-small-cell lung cancer cells." (PMID 22102859, 2011). "Thus, we aimed in our study to isolate the major triterpenes from the ethanolic extract of T. capitatus in order to investigate their underlying mechanism in inducing apoptosis via the regulation of Let-7 miRNA/Cyclin D1/VEGF cascade in non-small cell lung carcinoma (NSCLC)." (PMID 37845669, 2023). "Therefore, this study is designed to isolate the major triterpenes from the ethanolic extract of T. capitatus in order to investigate their underlying mechanism in inducing apoptosis via the regulation of Let-7 miRNA/Cyclin D1/VEGF cascade in non-small cell lung carcinoma (NSCLC)." (PMID 37845669, 2023). "Interestingly, in a KRAS-driven non-small cell lung cancer mouse model, ERK-induced concomitant upregulation of Ccnd1, as well as Ccnd3, was observed, rendering the tumor resistant to palbociclib." (PMID 35013097, 2022). "In addition, YTHDF1 promoted non-small cell lung cancer cell proliferation through regulating the translational efficiency of CDK2, CDK4, and cyclin D1." (PMID 33726814, 2021).
non-small cell lung carcinoma (continued). "Furthermore, up-regulated piR-651 in non-small cell lung carcinoma (NSCLC) may induce oncogene expression, such as cyclin D1 and cyclin-dependent kinase 4 (CDK4), although the exact mechanism remains unclear." (PMID 31399034, 2019). "Kla-TAT peptide and HPRP-A1 co-administration show synergistic effects on non-small cell lung cancer (NSCLC) A549 cells, including the promotion of mechanical disruption and apoptosis induced by a caspase-dependent pathway, and the arrest in G1 phase by the down-regulating cyclin-D1." (PMID 37239989, 2023). "However, higher cyclin D1 expression was found in galectin-3 negative tumor tissues and the differences in correlations between their expressions in two main histopathological types of non-small cell lung cancer were also discovered." (PMID 30410421, 2018). "Besides, puromycin proved to promote the function of farnesiferol c in downregulating CCND1 and CDK4 in non-small-cell lung cancer cells, which not only supports the scientific hypothesis but also provides a new clue for LGG treatments." (PMID 36703644, 2023).
B-cell lymphoma (87 papers, 2006 to 2026). "MCL is a mature B-cell lymphoma that characteristically expresses cyclin D1, which has been used as a diagnostic tumor marker." (PMID 31714947, 2019). "Furthermore, qRT-PCR and Western blot analysis were used to verify cyclin D1, Bcl-2 associated X, B-cell lymphoma/leukemia gene-2, and β-catenin levels." (PMID 38464761, 2024). "FISH demonstrated MYC, BCL2, BCL6, and CCND1 rearrangements and the diagnosis of high-grade B-cell lymphoma with MYC, BCL2, BCL6, and CCND1 was rendered." (PMID 38914869, 2024). "Aggressive mature B cell lymphomas should express B cell–associated antigens (e.g., CD20, CD19, CD79a) and lack cyclin D1." (PMID 31388760, 2019). "The results of the present study confirm that CCND1 is an important potential prognostic gene in canine B-cell lymphoma (especially DLBCL subtype) and should, accordingly, be considered for further investigation in future studies." (PMID 28069005, 2017). "The results of our study demonstrate that CCND1 is a favorable potential prognostic predictor for canine B-cell lymphoma." (PMID 28069005, 2017). "Alternatively, B-cell lymphoma also developed when crossing the Emu-CCND1 mouse with transgenic mice that had other genetic aberrations observed in MCL, such as BIM-deficient or ATM-deficient mice." (PMID 27713153, 2016). "Cyclin D1 nuclear overexpression induces differentiated phenotype in B-cell lymphoma in transgenic mice and drives the oncogenic transformation of murine fibroblasts." (PMID 26620414, 2015). "We previously reported that cyclin D1 inhibits mitochondrial activity in B-cell lymphoma, by competing with hexokinase 2 for binding to the voltage-dependent anion channel." (PMID 25881299, 2015). "B-cell lymphomas can be induced in transgenic mice expressing a cyclin D1 mutant (T286A) under the control of Eμ enhancer." (PMID 17022831, 2006). "In conclusion, although the results of the present study reveal CCND1 as a potential prognostic factor in canine B-cell lymphoma, further studies on more extensive gene expression databases are required to clarify other prognostic genes which can be used as robust survival predictors." (PMID 28069005, 2017). "qRT-PCR used for verification of results indicated that expression level of CCND1 was significantly higher in B-cell lymphoma patients with the long DFS than ones with the short DFS, while expression level of BIRCS5 wasn’t significantly different between two groups." (PMID 28069005, 2017). "MYC had been reported to cooperate with cyclin D1 to develop B cell lymphoma in transgenic mice." (PMID 26517511, 2015). "All cases were successfully tested for common breakapart molecular events for B-cell lymphomas and PCNLs, BCL6, BCL2, CCND1, IGH, IGL, IGK, and MYC." (PMID 38730692, 2024). "Cyclin D1 (CCND1) is required during the transition from G1 to S phase and is known to be overexpressed in B-cell lymphomas." (PMID 37670323, 2023). "It is especially interesting to examine the effect of AL928768.3 eRNA in the regulation of other oncogenes (CCND1, BCL-6) that are translocated into the IGH locus as a result of chromosomal rearrangements in B-cell lymphomas." (PMID 35563017, 2022). "B-cell lymphomas are characterized by chromosomal translocations of regions with important oncogenes and tumor suppressor genes, including C-MYC, Cyclin D1 (CCND1), B-cell lymphoma 2 (BCL2) and B-cell lymphoma 6 (BCL6)." (PMID 35740251, 2022). "Discrepancy between prognostic efficacy of the CCND1 in human (especially MCL) and canine B-cell lymphoma can be described in some ways." (PMID 28069005, 2017). "In general, cyclin D1 has been proposed as the most critical prognostic gene majorly in MCL and seldom for other human B-cell lymphoma subtypes." (PMID 28069005, 2017). "The term ‘DH lymphoma’ was initially used to describe mature-B-cell lymphomas with a chromosomal breakpoint affecting the MYC locus in combination with another recurrent breakpoint, such as BCL2, BCL6, BCL3 or CCND1." (PMID 26517511, 2015).
B-cell lymphoma (continued). "Furthermore, SOX11 may be expressed in other aggressive B cell lymphomas that lack cyclin D1." (PMID 21124928, 2010). "B-cell lymphomas with MYC, BCL2, BCL6, and CCND1 rearrangements are rare entities." (PMID 38914869, 2024). "However, the multivariate Cox proportional-hazard analysis confirmed CCND1 and BIRCS5 as prognostic genes for canine B-cell lymphoma." (PMID 28069005, 2017). "Immunohistochemical stain revealed that tumor cells were diffusely positive for CD20, CD79a, bcl-2, and negative for CD3, CD5, CD10, cyclin D1 and bcl-6, which excludes the possibility of low grade B-cell lymphoma other than EMZL." (PMID 26111022, 2015). "The absence of CD10, CD30, SOX11 and Cyclin D1 help rule out other B-cell lymphoma." (PMID 40896441, 2025). "Indeed, Ccnd1 was first characterized by studies of gene amplification as the gene affected by a chromosome inversion in parathyroid adenoma (PRAD1) and by a translocation t(11:14) in B-Cell Lymphomas (BCL-1)." (PMID 27105504, 2016). "Additionally, because it was a single-center study, the results might not accurately reflect the frequency of cyclin D1 expression in high-grade B-cell lymphoma." (PMID 36312606, 2022). "All B-cell lymphoma patients had CD20 staining, 4 (80%) had CD43 and Bcl2, 2 (40%) had CD3 and CD23 staining, while none of the patients had CD10 and Cyclin D1 staining." (PMID 38301095, 2023). "A repeat AC paracentesis was performed for cytological analysis, which revealed monoclonal B-cell lymphoma population positive for CD20, CD5, cyclin D1, and SOX11 but negative for CD10, CD3, and S100." (PMID 26450638, 2015). "B-cell lymphomas with concurrent MYC, BCL2, BCL6, and CCND1 rearrangements appear to be a rare occurrence; however, current standard approaches to DLBCL/HGBL classification do not require routine testing for CCND1 rearrangement." (PMID 38914869, 2024). "Unlike other aggressive B-cell lymphomas, BCL2 translocation may not occur in MCL, which indicates that BCL2 and CCND1 translocations might be mutually exclusive." (PMID 26517511, 2015).
lung adenocarcinoma (86 papers, 2010 to 2025). A carcinoma that arises from the lung and is characterized by the presence of malignant glandular epithelial cells. "Based on these findings, it was proposed that A. lanipes extract can inhibit the cell cycle by downregulating CCND1 and causing A549 lung adenocarcinoma cells to undergo apoptosis via modifying the expression of Bax, Bcl-2, and caspases." (PMID 40142097, 2025). "Overexpression of circACP6 can cause the initiation of lung adenocarcinoma via raising the expression of carcinogen cyclin D1 as a result of sponging miR-134." (PMID 36397164, 2022). "Expression of oncogenes including phospho-Src, phospho-β-catenin, c-myc, and cyclin D1 were also detected in the tumor-like tissues, as were diagnostic markers for lung adenocarcinoma, such as TTF1, NAPSA, CK7, and CK-HMW." (PMID 26871601, 2016). "The induced NF-κB, its downstream pathway and cyclin D1 were demonstrated to be associated with poor prognosis in lung adenocarcinoma." (PMID 27764170, 2016). "The effect of vorinostat on cyclin D1 expression was further analyzed because of our finding that cyclin D1 was significantly associated with poor RFS in stage II-IIIA lung adenocarcinoma." (PMID 26681199, 2015). "However, the high expression of CCND1 is associated with poor prognosis of head and neck squamous cell carcinoma, lung adenocarcinoma, mesothelioma and pancreatic adenocarcinoma." (PMID 31850854, 2019). "In summary, the present study suggests that cyclin D1 overexpression may be significantly associated with poor RFS in stage II-IIIA lung adenocarcinoma and its expression be modulated by vorinostat." (PMID 26681199, 2015). "Only cyclin D1 overexpression in the present study was significantly associated with poor RFS in stage II-IIIA lung adenocarcinoma, suggesting that histology may function as an effect modifier in the relationship between RFS and protein expression." (PMID 26681199, 2015). "In lung adenocarcinoma, Foxp3 upregulates CCND1 (a gene of cell cycle G1/s checkpoint); thereby enhancing lung adenocarcinoma." (PMID 35326661, 2022). "In lung adenocarcinoma cell lines, it was shown that apelin-13 promotes proliferation through the expression of cyclin D1 mediated by the phosphorylation of ERK1/2." (PMID 36291097, 2022). "For example, a homeobox transcription factor NKX2-1 was found to be involved in both the development and metastasis of lung adenocarcinoma and the activation of CCND1 through interacting with its promotor." (PMID 35365622, 2022). "As a cell cycle-regulatory protein, CCND1 can obviously inhibit the proliferation, infiltration and metastasis of lung adenocarcinoma A549 cells after down-regulation of its expression." (PMID 34806539, 2021). "In a study of a lung adenocarcinoma, miR-20b-5p was found to directly and independently inhibit the activity of reporter genes and decrease the CCND1 protein expression." (PMID 34068010, 2021). "Another study identified circPUM1 was significantly up‐regulated in lung adenocarcinoma and increased cyclin D1 and Bcl‐2 expression by sponging miR‐138‐5p, thereby facilitating cell proliferation, migration and invasion of lung adenocarcinoma." (PMID 34672397, 2021). "Hsa_circ_0013958 was characterized as a miR-134 sponge, leading to upregulated oncogenic cyclin D1 in lung adenocarcinoma." (PMID 32629833, 2020). "Our results showing the direct association between expression of cyclin D1, CDK4, and high pRb levels, strongly suggest activation of cyclin D1/CDK4 pathway in lung adenocarcinoma." (PMID 32104498, 2020).
lung adenocarcinoma (continued). "In keeping with our in vitro findings, we observed a mild but significant correlation (r = 0.33; p = 0.002) between SMARCA4 and CCND1 mRNA expression in a cohort of 83 lung adenocarcinomas (LUADs), a main NSCLC subtype." (PMID 30718506, 2019). "The results of the present study confirmed that cyclin D1 was a functional target of CASC9.5 in lung adenocarcinoma." (PMID 29311567, 2018). "Crebanine, an aporphine alkaloid, was reported to exert an anti-cancer activity through down-regulating cyclin D1 expression in lung adenocarcinoma A549." (PMID 30279365, 2018). "In the case of claudin-2, its nuclear distribution is up-regulated by dephosphorylation and serves to retain ZONAB and cyclin D1 in the nucleus, resulting in the enhancement of proliferation of lung adenocarcinoma cells." (PMID 27641742, 2016). "Here, we found that Cyclin D1 was a downstream regulator involved in HNF1A-AS1-mediated growth arrest in lung adenocarcinoma." (PMID 25863539, 2015). "The present experimental results confirmed that Cyclin D1 is a functional target of HNF1A-AS1 in lung adenocarcinoma." (PMID 25863539, 2015). "We used A549, a human lung adenocarcinoma epithelial cell line that expresses relatively high levels of cyclin D1, as our model to analyze the effect of vorinostat on cell growth." (PMID 26681199, 2015). "Forced over-expression of miR-186 in lung adenocarcinoma cells inhibits proliferation and invasion by targeting and inhibiting the cyclin D1, cyclin-dependent kinase 2 (CDK2), and CDK6 genes and pituitary tumor transforming gene." (PMID 25742499, 2015). "Cyclin D1 is a key regulator of cell cycle progression, it is found to be overexpressed in lung adenocarcinoma which is related to its increased proliferation." (PMID 23091605, 2012). "Immunohistochemical analysis demonstrated the up-regulation of the protein levels of Mcm2, Fen1, Ube2C and cyclin D1 in lung adenocarcinoma tissue of NNK-exposed Gprc5a-knockout mice compared to the levels in normal lung tissue obtained from the same mice." (PMID 20686609, 2010). "In addition, a recent study reported that KRT80 knockdown affected the cell cycle activity via CCND1 expression in lung adenocarcinoma cells." (PMID 40647481, 2025). "GEPIA revealed distinct clinical implications for FN1 and CCND1 in lung adenocarcinoma." (PMID 41301482, 2025). "Besides being the most studies model for lung adenocarcinomas, A549 cells were chosen for knocking down PD-L1 also because they had PD-L1 expression and a high level of CCND1 expression suggesting active proliferative drive." (PMID 39201772, 2024). "Interestingly, we observed the increased expression of cdk 2, 4, and 6 and cyclin D1, D3, and E1 following the loss of UBQLN1 and UBQLN2 in lung adenocarcinoma cells." (PMID 37444499, 2023). "CASC9 also regulates cell cycle progression in the G1 phase via cyclin D1 in lung adenocarcinoma." (PMID 35427373, 2022). "Moreover, blocking PFKFB3 activity with PFK15 resulted in a significant reduction in cyclin D1 expression in tumor cells isolated from lung adenocarcinoma after 24 h." (PMID 33922320, 2021). "SOX6 suppresses the cell cycle of lung adenocarcinoma by regulating cyclin D1, which indicated miR-1269a might be involved in radiation sensitivity." (PMID 34504628, 2021). "Finally, Western blotting results showed the mechanism of silibinin inhibiting lung adenocarcinoma was through apoptosis and downregulation of cyclin D1." (PMID 33935737, 2021). "Indeed, hsa_circ_0013958 in lung adenocarcinoma was shown to competitively interact with miR-134 and attenuate its repression of cyclin D1, thereby accelerating cell proliferation." (PMID 34565283, 2021). "HOXC13 promotes proliferation of lung adenocarcinoma via modulation of CCND1 and CCNE1." (PMID 31992202, 2020).